RUNX2 (RUNX family transcription factor 2)
Diseases named in the same sentence as RUNX2 in open-access papers (continued):
Sharing a sentence is not in itself a finding about the gene and the disease.
alcoholism (1 paper, 2021). "Long-term detrimental effects of alcoholism have toxic effects on BMMSCs and affect their differentiation into osteoblasts by downregulating the expression of Runx2, which in turn leads to low bone mass." (PMID 34745415, 2021).
Allergy (1 paper, 2013). An allergy is an immune response or reaction to substances that are usually not harmful. "Although RUNX2 is a widely expressed transcription factor, RUNX2 might be a new gene in the field of allergy, since its function now is only well understood in bone development." (PMID 24282527, 2013).
anaplastic thyroid cancer (1 paper, 2022). "In line with previous reports, we found that, TRβ1 expression is downregulated, while Runx2 is upregulated in follicular and anaplastic thyroid cancer cells, compared with primary thyroid epithelial cells." (PMID 36497320, 2022). "We next investigated the expression of TRβ1 and Runx2 in normal primary thyroid cells, and in follicular and anaplastic thyroid cancer cells." (PMID 36497320, 2022).
and dental disorder (1 paper, 2021). "Pathogenic variants of RUNX2, a gene that encodes an osteoblast-specific transcription factor, have been shown as the cause of CCD, which is a rare hereditary skeletal and dental disorder with dominant mode of inheritance and a broad range of clinical variability." (PMID 34217160, 2021).
aneurysmal bone cyst (1 paper, 2023). A locally aggressive and destructive benign cystic lesion of the bone. "The GCs of aneurysmal bone cyst were up to 30% RUNX2-positive, with the exception of sample 32a (incision biopsy), which was RUNX2-negative." (PMID 37509363, 2023). "The same reason may apply to the heterogeneity of RUNX2-expression in the GCs of aneurysmal bone cyst." (PMID 37509363, 2023).
ankylosis (1 paper, 2014). Fixation and immobility of a joint. "Previous reports show that tissue-specific inactivation of Shox2 in the cranial neural crest cells leads to TMJ dysplasia and ankylosis, accompanied by significant down-regulation of Sox9, Runx2 and Ihh." (PMID 25062348, 2014).
anorexia nervosa (1 paper, 2025). A disorder most often seen in adolescent females characterized by a refusal to maintain a minimally normal body weight, an intense fear of gaining weight, a disturbance in body image, and, in postmenarcheal females, the development of amenorrhea. "SIRT1 activation by resveratrol reduced BMA and promoted osteogenesis in an anorexia nervosa model by modulating the acetylation levels of Runx2 and FoxO1." (PMID 40243497, 2025).
aortic atherosclerosis (1 paper, 2017). A atherosclerosis that involves the aorta. "For example, the VSMC-specific deficiency of Runx2, a positive regulator of osteoblast differentiation, reduces calcification of atherosclerotic plaques in dyslipidemic apoE knockout mice, but fails to halt progression of aortic atherosclerosis in this model." (PMID 29023576, 2017).
aortic valve stenosis (1 paper, 2025). Aortic valve stenosis (AVS) is a condition characterized by narrowing of the heart's aortic valve opening. "High levels of RUNX2 in vascular smooth muscle cells can lead to osteogenic reprogramming causing calcification of the valves and aortic valve stenosis." (PMID 41511334, 2025).
astrocytoma (1 paper, 2023). "Of these subtypes, RUNX1, RUNX2, and RUNX3 in astrocytoma is higher than that oligodendroglioma." (PMID 36321611, 2023).
autism (1 paper, 2015). Persistent deficits in social interaction and communication and interaction as well as a markedly restricted repertoire of activity and interest as well as repetitive patterns of behavior. "Recently, RUNX2 has been shown to interact with several key candidate genes for autism, specifically with SMURF1, a gene involved in the regulation of axonogenesis." (PMID 26136701, 2015).
bladder tumors (1 paper, 2022). "Runt-related transcription factor 2 (RUNX2) is a key factor of osteoblast differentiation and has been reported to be associated with epithelial-mesenchymal transition in bladder tumors." (PMID 35063012, 2022).
bone metabolism disorders (1 paper, 2023). "Functional state changes of CREM, FOSL2, FOXC2, RUNX2, and CREB3L1 regulons regarding immunity, cell proliferation, and differentiation identified the important cell stages or subtypes that may be predominantly affected by bone metabolism disorders." (PMID 36793138, 2023).
bone sarcoma (1 paper, 2025). A sarcoma that arises from the bone. "RUNX2 is recognized for its role in bone sarcomas, where it regulates bone turnover and influences response to targeted therapies." (PMID 40989695, 2025).
Brachycephaly (1 paper, 2022). An abnormality of skull shape characterized by a decreased anterior-posterior diameter. "The results of these studies show association of brachycephaly with the RUNX2 gene on CFA12, SMOC2 on CFA1 and BMP3 on CFA32, chondrodysplasia with FGF4 retrogene on CFA12 and CFA18 and also with skull size." (PMID 36230363, 2022). "A missense mutation in BMP3 has been identified as a major contributor to brachycephaly, and a repeat expansion of the RUNX2 gene has been correlated with snout dorsiflexion and midface length in dogs." (PMID 36230363, 2022).
breast adenocarcinoma (1 paper, 2010). "Here, we show that expression of RUNX2 expression in MDA-MB-231 breast adenocarcinoma cells is reciprocally linked to mitogen-dependent enhancement of the MEK-Erk signaling pathway." (PMID 21029421, 2010). "We find that, similar to its regulation in osteoblasts, RUNX2 expression in MDA-MB-231 breast adenocarcinoma cells is enhanced upon growth factor deprivation, as well as upon deactivation of the mitogen-dependent MEK-Erk pathway or EGFR signaling." (PMID 21029421, 2010). "Rather, our results indicate that RUNX2 levels are functionally coupled to cell motility in MDA-MB-231 or when introduced into MCF7 breast adenocarcinoma cells." (PMID 21029421, 2010).
campomelic dysplasia (1 paper, 2024). "In humans, campomelic dysplasia caused by SOX9 haploinsufficiency is associated with chondrocyte hypertrophy and increased RUNX2 levels." (PMID 38885336, 2024).
cardiac hypertrophy (1 paper, 2025). "In pathological cardiac hypertrophy, the liquid–liquid phase separation (LLPS) of Runx2 has been identified as a regulated form underlying ventricular remodelling." (PMID 40159625, 2025).
cholestasis (1 paper, 2023). Impairment of the bile flow caused by obstruction within the liver, or outside the liver in the bile duct system. "The H&E staining verified that DDC or MCD successfully induced cholestasis or NASH in mice, and the level of fibrosis and HSC activation was significantly lower in Runx2‐deficient mice compared to the controls." (PMID 37403784, 2023).
chromophobe renal cell carcinoma (1 paper, 2023). Chromophobe renal cell carcinoma is a rare subtype of renal cell carcinoma, originating from the intercalating cells of the collecting ducts and macroscopically manifesting as a well-circumscribed, highly lobulated, solid tumor that is usually diagnosed at an early stage. "RUNX2 was upregulated in ccRCC and papillary renal cell carcinoma, and RUNX2 was downregulated in chromophobe renal cell carcinoma." (PMID 36200301, 2023).
Crohn disease (1 paper, 2025). A gastrointestinal disorder characterized by chronic inflammation involving all layers of the intestinal wall, noncaseating granulomas affecting the intestinal wall and regional lymph nodes, and transmural fibrosis. "Multiple omics analyses identified RUNX2 and BHLHE40 as key factors driving TRM characteristic of Crohn’s disease." (PMID 40906156, 2025).
cutaneous T-cell lymphoma (1 paper, 2024). "Interestingly, RUNX2 is connected to the RUNX3 gene which is already known to be dysregulated in cutaneous T-cell lymphoma, emphasizing the necessity of looking further into this gene as a potential biomarker." (PMID 39435287, 2024).
diabetic nephropathy (1 paper, 2018). "Our previous study provided evidence supporting involvement of the BMP-2/Smad1/Runx2/Osterix signaling pathway in the development of vascular calcification in diabetic nephropathy rats." (PMID 29850574, 2018).
Dolichocephaly (1 paper, 2021). An abnormality of skull shape characterized by a increased anterior-posterior diameter, i.e., an increased antero-posterior dimension of the skull. "Treatment of cranial suture cells with IgPKD1 for 6, 12 and 24 hours was found to significantly increase p‐RUNX2 levels in both trigonocephaly and dolichocephaly at all time‐points." (PMID 33656806, 2021).
dwarfism (1 paper, 2023). "However, there have been few reports of treatments based on Runx2-specific regulation targeting dwarfism symptoms." (PMID 36599929, 2023).
embryonic carcinoma (1 paper, 2012). "Not only Smad 5 but also Smads 2 and 3 were shown to physically interact with RUNX2 in P19 embryonic carcinoma cells." (PMID 22966907, 2012).
enthesopathy (1 paper, 2023). "Similar to Hyp entheses, C–/– entheses develop an expansion of SafO+, ALP+ cells that are immunoreactive for p-SMAD1/5/8, PTCH, and RUNX2 by P14, thus demonstrating that enthesopathy in both Hyp and C–/– mice develops early in the postnatal period." (PMID 37490334, 2023). "Ablation of the Vdr in Scx+ cells starting on P30, after enthesopathy has developed, does not alter staining for SafO or BMP and IHH markers PTCH and RUNX2 in entheses relative to control entheses." (PMID 37490334, 2023).
esophageal adenocarcinoma (1 paper, 2022). A malignant tumor with glandular differentiation arising predominantly from Barrett mucosa in the lower third of the esophagus. "The highest alteration frequency of RUNX2 (>6%) appeared for patients with esophageal adenocarcinoma with primary type “amplification”." (PMID 35522574, 2022).
Ewing sarcoma (1 paper, 2025). A small round cell tumor that lacks morphologic, immunohistochemical, and electron microscopic evidence of neuroectodermal differentiation. "The analysis involves a comparison of the median (min–max) expression levels of WWOX and RUNX2 in Ewing sarcoma cases (n=7) versus controls (n=5), based on tissue protein levels assessed via immunohistochemistry." (PMID 41141138, 2025). "A strength of this study is that it is among the first to simultaneously profile WWOX and RUNX2 in Ewing sarcoma, integrating molecular data with survival outcomes." (PMID 41141138, 2025). "Future large-scale, multi-institutional studies are warranted to validate RUNX2 as a prognostic marker, clarify the modulatory role of WWOX, and explore whether targeting this pathway can improve clinical outcomes in patients with Ewing sarcoma." (PMID 41141138, 2025).
extraskeletal osteosarcoma (1 paper, 2024). "Histopathology and immunohistochemical analysis revealed positive reactions for Vimentin, Runx-2 and ki-67, leading to a diagnosis of extraskeletal osteosarcoma (ESOS)." (PMID 39399861, 2024).
femoral neck fracture (1 paper, 2018). Fractures of the short, constricted portion of the thigh bone between the femur head and the trochanters. "Clinical samples obtained from femoral neck fracture patients’ bone tissues were used to collect circRUNX2, miR‐203, and RUNX2 expression data, while their expression changes were observed in human bone mesenchymal stem cells (hBMSCs) during osteogenic differentiation." (PMID 30324718, 2018).
follicular thyroid cancer (1 paper, 2022). "To study the functional significance of Runx2 in follicular thyroid cancer ML-1 cells, we downregulated it by siRNA." (PMID 36497320, 2022). "The knockdown of the calcium signalling proteins TRPC1, STIM1 and ORAI, increased the expression of TRβ1, but decreased that of Runx2 in human follicular thyroid cancer ML-1 cells." (PMID 36497320, 2022).
gastric tumors (1 paper, 2010). "The increased expression of the PPARδ target gene, Agptl4, the TGFβ-activated genes Runx1 and Runx2, and S100A8 and S100A9 in the gastric tumors indeed suggests a duality of function of both PPARδ and TGFβ signaling in gastric tumorigenesis." (PMID 21318167, 2010).
giant cell tumour (1 paper, 2018). "It was also noted in the connective tissue matrix around mononuclear cells in giant cell tumour of bone; these cells are known to exhibit several osteoblast markers including alkaline phosphatase, RUNX2, osterix and RANKL." (PMID 30202513, 2018).
glaucoma (1 paper, 2021). Increased pressure in the eyeball due to obstruction of the outflow of aqueous humor. "Another genetic variant in RUNX2 (rs1755056) was found to be significantly associated with IOP and weakly associated with POAG in a GWAS combing participants from the UK Biobank and published data from International Glaucoma Genetic Consortium." (PMID 34233613, 2021).
Gorlin syndrome (1 paper, 2017). "Thus, Gorlin syndrome patient-derived iPSCs are highly responsive to osteogenic differentiation induced by the overexpression of Hh genes and genes that encode various Hh-associated signaling molecules, including Wnts, BMPs, and RUNX2." (PMID 29088246, 2017).
Hallux valgus (1 paper, 2021). Lateral deviation of the great toe (i.e., in the direction of the little toe). "We examined the mRNA levels of osteogenic capability biomarkers Collagen-I, ALP, OPG, OCN and Runx-2, we found osteogenic hyperfunction in the first plantar toe joint of hallux valgus patients." (PMID 33456347, 2021).
Hearing impairment (1 paper, 2025). A decreased magnitude of the sensory perception of sound. "Finally, the PPI networks identified in this study, particularly those involving RUNX2, TGFB2, and CDH1, may serve as the foundation for novel therapeutic approaches aimed at restoring auditory function in patients who have already experienced radiotherapy-induced hearing impairment." (PMID 40362371, 2025).
hearing-loss (1 paper, 2025). "The protein–protein interaction network analysis identified prominent interaction characteristics among neighboring genes of tinnitus-associated loci (RUNX2, TGFB2, CDH1, and DEFB family) and hearing-loss-associated loci (CDH1, PRR19, and MAGOHB)." (PMID 40362371, 2025).
HTLV infection (1 paper, 2022). "Despite this evidence, RUNX2 has never been studied in the context of HTLV infection, until now." (PMID 35886938, 2022).
hypertensive nephropathy (1 paper, 2024). Kidney damage that results from chronically elevated blood pressure; complications include glomerular damage resulting in proteinuria and hematuria. "The miR/RAS/RUNX2 autophagy network driven by H2S donors was related to hypertensive nephropathy." (PMID 39199205, 2024). "Collectively, in the hypertensive nephropathy samples and AngII-induced podocyte models, the renal injury markers were increased, autophagic flux was decreased, and differential miRNAs (miR-98-5p and miR-669b-5p), hub target genes (KRAS and NRAS), and transcription factor (RUNX2) were dysregulated." (PMID 39199205, 2024).
hyperuricemia (1 paper, 2022). An abnormally high level of uric acid. "Runx2 is a relevant biomarker, because medications such as allopurinol reduce osteoblast apoptosis, increase their viability, and reduce the risk of vascular calcification by decreasing Runx2 in animal models of hyperuricemia." (PMID 36556927, 2022).
Kallmann syndrome (1 paper, 2025). Kallmann syndrome (KS) is a developmental genetic disorder characterized by the association of congenital hypogonadotropic hypogonadism (CHH) due to gonadotropin-releasing hormone (GnRH) deficiency, and anosmia or hyposmia (with hypoplasia or aplasia of the olfactory bulbs). "SNPs in genes involved with syndromes were previously associated with a variety of facial measurements, for example, genes such as FGFR1 (e.g., Pfeiffer syndrome and Kallmann syndrome), IRF6 (e.g., Van der Woude syndrome), and RUNX2 (e.g., cleidocranial dysplasia syndrome)." (PMID 40303982, 2025).
knee osteoarthritis (1 paper, 2023). "High expression of RUNX2 leads to chondrocyte hypertrophy and cartilage extracellular matrix decomposition, promoting cartilage degeneration in knee osteoarthritis cartilage." (PMID 36915153, 2023). "In knee osteoarthritis cartilage, high expression of RUNX2 and DKK-1 leads to chondrocyte hypertrophy and cartilage extracellular matrix decomposition, promoting cartilage degeneration." (PMID 36915153, 2023).
Limb ataxia (1 paper, 2026). A kind of ataxia that affects movements of the extremities. "In mice, Runx1 knockout abolishes definitive haematopoiesis, Runx2 deficiency impairs bone formation, and Runx3 loss leads to limb ataxia due to neuronal death during embryogenesis." (PMID 41550415, 2026).
limb-girdle myopathy (1 paper, 2017). "We described limb-girdle myopathy in a patient with CCD that carried a heterozygous RUNX2 missense mutation." (PMID 28056872, 2017). "Here, we described a patient with CCD that exhibited an uncommon initial manifestation of late-onset, limb-girdle myopathy, due to a missense mutation (c.G674A, p.R225Q) in the RUNX2 gene." (PMID 28056872, 2017). "Here, we describe limb-girdle myopathy, an uncommon phenotype in CCD, in a patient with a heterozygous missense mutation in the RUNX2 gene." (PMID 28056872, 2017). "Here, we describe limb-girdle myopathy, an uncommon phenotype of CCD, in a patient with a heterozygous missense mutation (p.R225Q) in the RUNX2 gene." (PMID 28056872, 2017).
lipoma (1 paper, 2018). A benign, usually painless, well-circumscribed lipomatous tumor composed of adipose tissue. "Although there are no studies on gene expression in isolated cells some research groups investigated the differences in expression of ADIPOQ, LEP and PPARG, RUNX2 and BGLAP in lipoma tissue and compared it with normal adipose tissue." (PMID 30544806, 2018).
lymphoid tumours (1 paper, 2014). "Indeed we note high levels of MYC in the lesions, which has been shown previously to be a strong collaborating event with RUNX2 in lymphoid tumours." (PMID 24626992, 2014).
malignant mesothelioma (1 paper, 2016). A malignant neoplasm of the pleura or peritoneum, arising from mesothelial cells. "Malignant mesothelioma cells were screened for the expression of markers associated with the osteoblast cell lineage; RUNX2, SPARC and SPP1." (PMID 27886205, 2016).
mantle cell lymphoma (1 paper, 2022). Mantle cell lymphoma is a rare form of malignant non-Hodgkin lymphoma affecting B lymphocytes in the lymph nodes in a region called the ``mantle zone''. "Mechanistically, MANCR acts as a miRNA sponge to sequester miR-218, which targets RUNX2, in mantle cell lymphoma." (PMID 35893239, 2022).
medulloblastoma (1 paper, 2020). A malignant, invasive embryonal neoplasm arising from the cerebellum. "For Group 4 medulloblastomas, B naïve cells were positively correlated with RUNX2 (p = 0.031, r = 0.208) and PITRM1 (p = 0.025, r = 0.214) expression, and the latter was negatively correlated with memory B cells as well (p = 0.048, r = −0.198)." (PMID 32508873, 2020). "Interestingly, the fraction of M2 macrophages in Group 4 medulloblastoma were positively correlated with the risk score and were significantly correlated with the expression level of four signature genes (CCNY, SYNE3, CYB5D2, and SELENOV) and four hub genes (GLI2, PAX6, RUNX2, and ZIC1)." (PMID 32508873, 2020).
meningioma (1 paper, 2007). A generally slow growing tumor attached to the dura mater. "In line with the microarray data, the PCR data showed a decrease in the median expression level of BMP4, SMAD9, JUN, RUNX2 and an increase in the median expression level of FKBP1A in Grade 3 meningiomas when compared to Grade 1 meningiomas." (PMID 17937814, 2007).